MDK (midkine)
Diseases named in the same sentence as MDK in open-access papers (continued):
Sharing a sentence is not in itself a finding about the gene and the disease.
tumor (continued). "Cell adhesion molecules such as ITGA3, CD47, MDK, ITGB1, CD55, and CDH1 show a trend of upregulation with pseudotime, indicating that cell-cell communications play an important role during the evolutionary process of tumor growth and progression." (PMID 35087839, 2021). "It is interesting to note that the concentration of midkine does not increase with primary tumor stage and UICC classification, but does tend to be elevated in the case of high‐grade tumors." (PMID 31984657, 2020). "Currently, co-targeting of dormant tumor cells and MyoCAFs by therapeutic inhibition of MDK and IGFBP7 is not available." (PMID 32460812, 2020). "Interestingly, the existence of a tumor cell subpopulation and MyoCAFs that express high levels of IGFBP7 and MDK contributing to tipifarnib failure was unveiled by scRNA-seq in this study." (PMID 32460812, 2020). "The survival of GBM tumor spheres was significantly decreased in a dose-dependent manner after treatment with two independent Chk inhibitors, AZD7762 and CHIR-124 compared to treatment with MDK neutralization alone." (PMID 31811117, 2019). "A novel small molecule compound (iMDK) targeted MDK demonstrated by Hao could suppress the growth of H441 cells by inhibiting the PI3K pathway and significantly inhibit tumor growth in a mouse model." (PMID 29872508, 2018). "For the first time, we illustrated the link between MDK and PDK1/AKT pathway in tumor angiogenesis." (PMID 30001734, 2018). "Third, midkine, a ligand that activates mammalian ALK, is produced by NF1−/− Schwann cells, present at elevated levels in NF1 patient skin and serum, and acts as a mitogen for NF1 tumor cell lines." (PMID 24278035, 2013). "Additionally, MDK (3.99), NME1 (4.82), and PA2G4 (4.21) showed increased expression in the tumor tissues from the patients with recurrent HCC." (PMID 24377043, 2013). "Other tumor-specific promoters used to drive E1-mediated virotherapy against various cancers include mucin-1 promoter, osteocalcin promoter, AFP promoter, midkine promoter, and COX-2 promoter." (PMID 23484134, 2013). "Possible midkine contribution to divergence in molecular patterns involved in promoting tumor progression between CRC with different location has not been evaluated before as well." (PMID 22562257, 2012). "These biomarkers includes catecholamines, ferritin, LDH, and other factors such as midkine, RANKL and OPG but they do not define all risk groups and they can not substitute the analysis of the tumor mass." (PMID 20624283, 2010). "Notably, CellChat analysis unveiled diverse and extensive interactions between PCD-related cell clusters and tumor immune cells, highlighting the CEBPB+ CAF subtype as a signaling ligand communicated with other immune cell clusters through the Midkine (MDK)-Nucleolin (NCL) signaling axis." (PMID 40145099, 2025). "Similarly, enhanced activity of the MDK-NCL and ANXA1-FPR1 signaling axes may contribute to tumor immune evasion by promoting macrophage recruitment, driving polarization toward an immunosuppressive phenotype." (PMID 41383622, 2025). "This supports that MDK-NCL may promote an immune-resistant TME through T cell exclusion rather than direct T cell exhaustion, a mechanism distinct from PD-1/PD-L1, which primarily induces T cell dysfunction at the tumor-immune interface." (PMID 40396179, 2025). "Additionally, MDK–NCL/SDC2/SDC4 interactions played a central role in CAF interactions with other cells, while CD99–CD99 interactions were widely involved in communications between immune cells and tumor cells." (PMID 40260248, 2025). "MDK was pathologically expressed in human SCLC tumor tissues but not in normal lung tissues." (PMID 40620228, 2025).
tumor (continued). "In a patient who exhibited markedly increased s‐MDK levels after four cycles of chemotherapy, the tumor progressed immediately after chemotherapy, although no increase in the expression of pro‐gastrin‐releasing peptide, a representative SCLC marker, was observed." (PMID 40620228, 2025). "Knockdown of midkine showed no evident influence on tumor growth of subcutaneous Hepa 1-6 tumors." (PMID 36906597, 2023). "Besides, anti-PD-1 antibody showed no obvious suppression on tumor growth of sorafenib-treated tumors, but this was greatly strengthened by midkine knockdown." (PMID 36906597, 2023). "Thus, when AK progresses to primary cSCC, MDK may further promote fibroblast proliferation, allowing it to regulate ECM remodeling and protect tumor cells from escaping the microenvironment." (PMID 36438481, 2022). "Thus, MDK potentially drives the proliferation and EMT of tumor cells in recurrent cSCC." (PMID 36438481, 2022). "Moreover, qRT-PCR verified seven apoptosis-related genes (APP, DOCK8, IFI44, MDK, SLC27A2, TNFAIP2, WNT5A) with at least 2 fold changes by means of 2−ΔΔCt method, finding that APP, SLC27A2 and WNT5A had a low expression, while DOCK8, IFI44, MDK, TNFAIP2 had a high expression in ccRCC tumor tissues." (PMID 33748185, 2021). "In addition, PCBP4 silencing significantly inhibited tumor sphere formation, while the tumor sphere area of the NT control cells did not decrease upon MDK inhibition (p < 0.5 and p < 0.01 for shPCBP4-1 and -2, respectively)." (PMID 31811117, 2019). "The subgroup analysis of tumor type demonstrated negative impact of elevated MDK on OS in most solid tumor patients (P < 0.05), while MDK had no relevance with OS in the patients with OSCC (pooled HR = 1.68; 95% CI = 0.84–3.36; P = 0.145) or HNSCC (pooled HR = 1.56; 95% CI = 0.96–2.51; P = 0.075)." (PMID 29872508, 2018). "The unexpected finding of the lack of correlation between the serum midkine levels and tumor progression in patients with NSCLC may be because of the relatively small number of patients with NSCLC who were recruited in our cohort." (PMID 27974680, 2016). "Although the reasons why the serum midkine concentrations do not parallel tumor progression remain to be elucidated, midkine may be very valuable as a convenient early detection biomarker in patients with NSCLC." (PMID 27974680, 2016). "MDK was found in cells within the tumour nests, but there was no staining in normal skin." (PMID 24163262, 2013). "In our scRNA-seq dataset, tumor cells had the highest expression of MIF and MDK, while other populations, such as monocytes/macrophages, had only low expression, suggesting that tumor cells may be the major source of MIF and MDK affecting lymphocyte cytotoxicity." (PMID 39908652, 2025). "Additionally, the MDK-NCL pathway suppresses cytotoxic immunity by reducing activated and effector memory CD8+ T cells while promoting an immunosuppressive microenvironment through increased Tregs and altering helper T cell differentiation, facilitating tumor immune evasion." (PMID 40396179, 2025). "However, they may also promote tumor progression through GAS6-AXL and ANXA1-FPR1 signaling, interacting with fibroblasts, endothelial cells, and monocytes, while the role of MDK-SDC2 and MDK-(ITGA4+ITGB1) signals remains to be elucidated." (PMID 39776914, 2024). "Next, to investigate whether MDK-driven immune-suppression dampens the effect of immune checkpoint blockade (ICB) therapy, we developed a humanized mouse model engrafted with pre-nodal cells from the tumor culture of patient HN279 and treated the mice with PD1-blockade." (PMID 36973261, 2023). "The virus is capable of killing tumor cells and even though the growth factor MDK itself is not involved in this kind of therapy, its solely expression in cancer tissues allows a tumor-selective replication of the virus containing the MDK promotor and might be a promising new cancer therapy." (PMID 38098484, 2023).
tumor (continued). "Another possible reason why the distribution of midkine in peripheral blood might not always be consistent with its expression in tumor tissues is because the IHC results for midkine expression are presented as both staining intensity and the percentage of positive staining cells." (PMID 27974680, 2016). "PD-1 blockade showed no obvious inhibition on tumor growth of sorafenib-treated HCC tumors, but the inhibitory effect was greatly enhanced by midkine knockdown." (PMID 36906597, 2023). "We successfully validated the presence of MDK and absence of STAT6 proteins in corresponding patient tumor tissues of cluster 4 GBM members, with GBM tissues from cluster 1 member GB-300 serving as positive control for STAT6." (PMID 34502484, 2021). "In conjunction with these data, IHC analysis of the patient tumor revealed that Ki-67-negative, non-cycling cells showed a higher immunoreactivity against IGFBP7, MDK, and B2M." (PMID 32460812, 2020). "In practice, if the AFP is negative (<20 IU/ml) but MDK elevated (≥0.44 ng/ml), a higher index of suspicion for an AFP-negative tumour is warranted." (PMID 27219517, 2016). "The serum midkine levels were elevated in patients with NSCLC, regardless of the clinicopathological features of the tumor, such as differentiation and TNM stage." (PMID 27974680, 2016). "Midkine was assessed immunoenzymatically in paired cancerous and noncancerous tissues from 53 CRCs and referred to CRC stage, tumor location, and size, and circulating cytokine levels." (PMID 22562257, 2012). "Within the present study cohort, plasma concentrations of MDK and AGR2 were not significantly altered by tumor type or stage of disease." (PMID 20525245, 2010). "However, since the correlation between AFP, GPC3, MDK, DKK1 and FNDC4 is not high, the sensitivity of FNDC4 as a tumor marker still needs further study." (PMID 38021165, 2023). "However, MDK and combinations of AFP + MDK, GPC3 + OPN have not been studied yet, therefore, it is a question of future research to investigate effectiveness of using these tumor markers in combination." (PMID 34513063, 2021).
cancer (181 papers, 1999 to 2026). A tumor composed of atypical neoplastic, often pleomorphic cells that invade other tissues. "Both SPP1-CD44 and MDK-NCL interactions are implicated in cancer progression and represent potential therapeutic targets." (PMID 39955556, 2025). "Cancer stem cells are major mediators of therapy resistance, and MDK-mediated enhancement of cancer stem cells has been linked with improved cancer stem cell survival following epirubicin treatment." (PMID 40429950, 2025). "It found that cancer cells transmit malignant phenotypes to endothelial cells via MDK-NCL signaling, which is linked to immune suppression, suggesting a role in TME modulation." (PMID 40777026, 2025). "Conversely, cancer-associated fibroblasts communicate with epithelial cancer cells via MDK targeting SDC2/SDC4/NCL on the epithelial cell surface." (PMID 40429950, 2025). "MDK has garnered attention as a therapeutic and diagnostic target for several cancers; however, only a few studies have evaluated its expression and function in SCLC." (PMID 40620228, 2025). "Cancer-associated fibroblast-secreted MDK has also been implicated in facilitating cellular survival after radiation therapy by promoting glycolysis and DNA repair via activation of the Wnt/β-catenin pathway." (PMID 40429950, 2025). "In cancer, MDK expression is generally associated with the activation of pro-survival signaling, angiogenesis, and epithelial-to-mesenchymal transition." (PMID 41463631, 2025). "MDK is overexpressed and has diagnostic and prognostic potential in several cancers, including lung, bladder, esophageal, and breast cancer." (PMID 40835683, 2025). "Research on midkine (MDK) has escalated in the last few decades, which affirms a positive correlation between disease progression and MDK expression in most cancers and indicates its association with multi-drug resistance in cancer." (PMID 37240085, 2023). "MDK encodes a secreted growth factor that promotes cell growth, migration, and angiogenesis and improves the stem-like properties of cancer cells." (PMID 36950551, 2023). "To clarify the function of MDK in tumorigenesis, we performed both loss-of-function and gain-of-function analyses of MDK in different cancer cell lines." (PMID 35487917, 2022). "MDK has been widely presumed to be a diagnostic marker of several different cancers, but the ambiguous regulatory molecular mechanism has postponed its utilization." (PMID 35487917, 2022). "We also identified several genes previously linked to cancer progression, such as midkine (MDK), SOX4 and LYZ1,31." (PMID 34764257, 2021). "We also show that midkine (MDK) expression in CTCs from metastatic hormone-sensitive prostate cancer (mHSPC) was associated to short cancer-specific survival (CSS)." (PMID 31877738, 2019). "The results of numerous clinical trials have suggested that high MDK expression is associated with shorter overall survival (OS) in various types of cancers." (PMID 29872508, 2018). "Midkine (MK) has been reported as the potential novel diagnostic biomarker for cancer in several studies, but their results were controversial." (PMID 28686647, 2017). "Numerous investigations have revealed an association between midkine expression in malignant tumors with the clinicopathological and prognostic significance." (PMID 27974680, 2016). "MDK is a growth factor associated with cancer development, often related to drug-resistance, that increases AKT proteins activation." (PMID 19753302, 2009). "Additionally, MDK from cancer-associated fibroblasts upregulated multidrug resistance protein 1 and multidrug resistance protein 2 to promote export of cisplatin from the cell." (PMID 40429950, 2025). "Upregulated genes in mEPCs, including IGF2, GPC3, S100A4, STMN1, and MDK, were semi-automatically assigned to the traditional cancer hallmark framework 15, including proliferative signaling, invasion/metastasis, genomic instability, immune response, and stem cell-like program." (PMID 36198671, 2022).
cancer (continued). "The MDK encoded protein promoted cancer cell growth, metastasis, and angiogenesis." (PMID 36483553, 2022). "Collectively, our data uncover a MDK-dependent EMT inducing mechanism underlying IFN-γ-driven metastasis across cancers which could be attenuated by pharmacological inhibition of MDK." (PMID 35747815, 2022). "Additionally, MDK has also been implicated in promoting cancer proliferation, angiogenesis, stemness, drug resistance, immunosuppression, and resistance to immune checkpoint blockade, closely correlated with advanced cancer progression and poor survival." (PMID 35747815, 2022). "In addition, MDK also has been linked to cancer cell invasion and metastasis via epithelial-mesenchymal transition (EMT) which has three major pathways: WNT signaling, TGF-β signaling, and Notch2 signaling pathways." (PMID 32847073, 2020). "Moreover, OSA causes a modulation of the microenvironment that favors cancer progression through the persistence of immunosuppression and the induction of various proangiogenic factors, such as vascular endothelial growth factor and midkine." (PMID 34359789, 2021). "Moreover, MDK was associated with relapse free survival in patients with cancers." (PMID 29872508, 2018). "A series of sulfated oligosaccharides (one tetra- and ten disaccharides) have been synthesized to study their interactions with midkine, a heparin-binding growth factor involved in cancer and inflammation." (PMID 41891761, 2026). "Here, we summarize current knowledge of MDK's immunoregulatory functions across various cancer types and propose a conceptual framework that positions MDK as a converging node linking oncogenic signaling with immune escape." (PMID 42004035, 2026). "Midkine (MDK), a secreted heparin-binding growth factor, has recently emerged as a regulator of the cancer-immune interface." (PMID 42004035, 2026). "The mechanisms through which MDK modulates cancer progression involve interactions with key receptors and downstream pathways." (PMID 40500394, 2025). "Recent studies suggest a strong association between MDK expression, multidrug resistance (MDR), and cancer development." (PMID 40500394, 2025). "Recently published studies have indicated that MDK is a potential therapeutic target and a biomarker for the progression of women’s cancer." (PMID 40429950, 2025). "As a specific type of MK signaling pathway, the role of MDK-NCL signaling network in cancer has been extensively studied." (PMID 40725006, 2025). "Ongoing translational research aims to establish MDK as a viable target in gene therapy and cancer treatment, offering a novel approach in oncology." (PMID 40500394, 2025). "The results of the cell communication analysis showed that the MDK signaling pathway played an important role in the communication between cancer cells and M1 macrophages in EGFRvIII-mutant GBM." (PMID 40527884, 2025). "Similar findings have been reported in cancer cells, where midkine activates the PI3K/Akt pathway to promote cell survival." (PMID 40969143, 2025). "As expected, overexpression of MDK in cancer cells led to increased mRNA and protein production of MDK." (PMID 40520001, 2025). "We further showed that MDK is involved in cancer-promoted osteoclastogenesis and that Ugonin P suppresses this process by upregulating miR-223-3p expression." (PMID 40520001, 2025). "In this review, we have provided a concise summary of the most recent papers that have examined the potential biomarker and therapeutic utility of MDK signaling in women’s cancer." (PMID 40429950, 2025). "MDK is overexpressed in several cancers and mediates resistance to chemotherapeutic drugs via several mechanisms." (PMID 40620228, 2025). "Midkine (MDK) is a heparin-binding growth factor implicated in the pathogenesis of various diseases, including cancer, chronic inflammation, and multidrug resistance (MDR)." (PMID 40500394, 2025).